RN7SK (RNA component of 7SK nuclear ribonucleoprotein)
Synonyms: 7SK
Gene: Small nuclear RNA gene on chromosome 6 (52,995,621 to 52,995,948, forward strand). Ensembl gene ENSG00000283293.
Diseases named in the same sentence as RN7SK in open-access papers:
RN7SK is named in the same sentence as 9 diseases in open-access papers, as found by Europe PMC text mining. Sharing a sentence is not in itself a finding about the gene and the disease. The quoted sentences say what the papers report.
autoimmune disease (1 paper, 2021). A disorder resulting from loss of function or tissue destruction of an organ or multiple organs, arising from humoral or cellular immune responses of the individual to their own tissue constituents. "So, upregulated RN7SK RNA may cause disturbance in the P-TEFb complex with resulting regulation effects on CD4+ T cells, thus participating in autoimmune diseases such as idiopathic inflammatory myopathy (IIM) and MS." (PMID 34950142, 2021).
cardiac hypertrophy (1 paper, 2016). "Furthermore, immunoprecipitation assays identified increased Rn7sk dissociation from the P-TEFb complex, which was shown to be important for RNA pol II activation and cardiac hypertrophy." (PMID 27270731, 2016).
prostate carcinoma (1 paper, 2024). A carcinoma that arises from epithelial cells of the prostate gland. "Components of the ribonucleoprotein (RN7SK genes) and Y RNA, part of long noncoding RNAs, were significantly upregulated in prostate cancer from AA men < 55 years compared to EA men < 55 years." (PMID 38566104, 2024).
tumor (5 papers, 2020 to 2025). "Additionally, RN7SK is an lncRNA that has been shown to be associated with a positive feedback circuit through interaction with m6A readers in tumor cells, which increases cellular proliferation." (PMID 41303378, 2025). "RN7SK expression is significantly downregulated in stem cells and human tumor tissues, and its overexpression enhances." (PMID 33362791, 2020). "Specifically, four genes (RN7SK, TNFRSF11B, NDUFB5 and RARRES3) were shown to be progressively up-regulated in primary and recurrent tumours compared to normal." (PMID 34062972, 2021).
cancer (2 papers, 2014 to 2024). A tumor composed of atypical neoplastic, often pleomorphic cells that invade other tissues. "A better understanding of the relationship of RN7SK with cytokines and cancer cell invasion will be necessary for elucidating its correlation with rhBMP-2 and cancer invasion." (PMID 25271422, 2014).
RN7SK also shares sentences with these, for which no sentence is quoted: HIV-1 infection (1 paper); idiopathic inflammatory myopathy (1); neurodevelopmental disorder (1); Obesity (1).